MTOR (mechanistic target of rapamycin kinase)
Diseases named in the same sentence as MTOR in open-access papers (continued):
Sharing a sentence is not in itself a finding about the gene and the disease.
cardiac hypertrophy (continued). "The role of PI3K/Akt/mTOR pathway in cardiac hypertrophy has been fully demonstrated." (PMID 33778070, 2021). "It has been proven that mTOR plays an important role in myocardial hypertrophy." (PMID 34007292, 2021). "The mammalian target of rapamycin (mTOR) pathway plays a key regulatory function in cardiovascular physiology (embryonic development, maintenance of cardiac structure and function) and pathology (cardiac hypertrophy, ischemia)." (PMID 34768351, 2021). "Antioxidants attenuate pathological cardiac hypertrophy through inhibiting mTOR or TGF-β1." (PMID 34007292, 2021). "Dioscin improves cardiac hypertrophy by inhibiting the Akt/GSK3β/mTOR pathway." (PMID 33778070, 2021). "Our results demonstrate that cardiomyocytes treated with AZD2014 retain the normal phenotype and AZD2014 attenuates cardiac hypertrophy in the Mybpc3-KO mouse model through inhibition of dual mTORC1 and mTORC2, which in turn results in the down-regulation of the Akt/mTOR signaling pathway." (PMID 34674743, 2021). "Inhibition of mTOR activation is beneficial in pressure overload-induced myocardial hypertrophy." (PMID 34007292, 2021). "mTOR is considered to be essential for pressure overload-induced pathological cardiac hypertrophy." (PMID 34540911, 2021). "Besides increasing cell size, cardiac hypertrophy involves increased protein synthesis controlled by the PI3K/AKT/mTOR pathway." (PMID 32595507, 2020). "MiR-199a targets the glycogen synthase kinase 3β (GSK3β)/mammalian target of rapamycin (mTOR) complex signaling pathway to impair cardiomyocyte autophagy and thereby enhancing cardiac hypertrophy (miR-199a impairs autophagy and induces cardiac hypertrophy through mTOR activation)." (PMID 33392270, 2020). "Therefore, one of the mechanisms of cardiac hypertrophy is mediated by activation of the PI3K/Akt/mTOR signaling pathway under TLR4 stimulation, which brings a detrimental effect on the heart." (PMID 33324685, 2020). "Repression of the activity of mTOR by rapamycin can inhibit cardiac hypertrophy in rodents." (PMID 32347291, 2020). "Besides, previous studies have demonstrated that mTOR inhibitor rapamycin is a promising drug for the treatment of cardiac hypertrophy in rodents." (PMID 32347291, 2020). "In conclusion, persistent induction of Gfat1 in the heart may directly activate mTOR signaling, induce pathological cardiac hypertrophy, and exacerbate cardiomyopathy under hemodynamic stress." (PMID 32286306, 2020). "There has been some research highlighting the cross-talk between Hippo and mTOR signaling during disease states of increased cell growth and proliferation such as cancer, however, very little is known with regards to cardiac hypertrophy." (PMID 32083081, 2020). "Additionally, because mammalian target of rapamycin (mTOR) is another key downstream target of AMPK in the regulation of cardiac hypertrophy, we performed western blotting to assess the phosphorylation and expression of mTOR in vivo and vitro." (PMID 32209725, 2020). "Additionally MIAT expression is upregulated in cardiomyocytes under AngII treatment, participating as an inducer of cardiac hypertrophy by activation of the PI3K/Akt/mTOR pathway via TLR4 upregulation by sponging miR-93 in cardiomyocytes." (PMID 32754048, 2020). "Short-term Akt activation improves contractile function in the failing hearts independent of hypertrophy; however, chronic Akt activation induces cardiac hypertrophy by activating mammalian target of rapamycin (mTOR) in transgenic mice with constitutively active Akt." (PMID 32831633, 2020). "One of the central targets of AKT during cardiac hypertrophy is mTOR." (PMID 32347291, 2020). "As increased protein synthesis is an important criteria for hypertrophy, activation of mTOR might be an important pathway through which TH induce cardiac hypertrophy." (PMID 31092832, 2019).
cardiac hypertrophy (continued). "Therefore, it is plausible that the elevation of local BCAA concentration observed can lead to chronic induction of cardiac mTOR activity, in turn, promoting cardiac hypertrophy observed under normal physiological conditions in NMRs." (PMID 31771414, 2019). "Partial mTOR inhibition through either pharmacologic or genetic inhibition exerted cardioprotective effects on several subtypes of cardiomyopathies, such as cardiac hypertrophy, lamin A/C-deficient DCM, and anemia and doxorubicin-induced cardiomyopathies (DIC)." (PMID 31492659, 2019). "Most notably, AKT1-Ser473 phosphorylation as well as levels of phospho-ERK1/2, phospho-mTOR, and phospho-p38MAPK were significantly elevated in the Mat-Ob group, suggesting an active role of mTOR in the development of cardiac hypertrophy upon diet-induced maternal obesity." (PMID 30305865, 2018). "Interestingly, mice displayed an increase in mTOR activity starting at first week through 8 weeks following TAC- (transverse aortic constriction-) induced cardiac hypertrophy." (PMID 30305865, 2018). "However, the exclusive interplay between lncRNA Plascr4 and mTOR in regulation mediated by miR-214 of cardiac hypertrophy is yet to be identified." (PMID 30305865, 2018). "Mammalian target of rapamycin (mTOR) has emerged as an important regulator of cardiac hypertrophy." (PMID 27190998, 2016). "mTOR signalling pathway is a critical regulator of cardiac hypertrophy." (PMID 26795633, 2016). "Pretreating the NCMs with rapamycin could significantly decrease the mRNA level of ANP and BNP, indicating that mTOR was involved in the PA-induced cardiac hypertrophy." (PMID 27057269, 2016). "p38γ/δ signalling through mTOR complexes is an important mediator of cardiac hypertrophy, and this pathway may also be important in other physiological processes mediated by mTOR, such as cancer and autophagy." (PMID 26795633, 2016). "To investigate whether mTOR is involved in the development of cardiac hypertrophy, we assessed mTOR protein expression using western blotting analysis." (PMID 26914935, 2016). "Data exist show that mTOR expression could be regulated by miR-99a, and mTOR/P70/S6K signaling pathway played an important role in cardiac hypertrophy." (PMID 26914935, 2016). "Previous studies had revealed that Six1 and its cofactor Eya2 could simulate heart hypertrophy through directly up-regulating mTOR." (PMID 27007909, 2016). "Hence, given the primary central role of Akt–mTOR signaling in swimming-induced cardiac hypertrophy, we explored the impact of moderate-intensity treadmill exercise on mTOR signaling and then perturbed the pathway with bolus DOX administration." (PMID 25991723, 2015). "A local elevation of BCAA concentrations may lead to chronic induction of mTOR, promoting cardiac hypertrophy by altering insulin sensitivity." (PMID 26267065, 2015). "Notably, this hypertrophic response was prevented by rapamycin, an mTOR inhibitor, suggesting that the Akt/mTOR pathway, rather than glycogen accumulation, plays a dominant role in mediating cardiac hypertrophy associated with the N488I PRKAG2 mutation." (PMID 40860364, 2025). "In addition, NR4A1 regulates mTOR signaling in angiotensinαII-induced cardiac hypertrophy; NR4A1 also enhances muscle mass in mice through IGF1-induced activation of mTOR, and in a mouse model of Parkinson’s disease the anti-inflammatory effect of NR4A1 is also associated with NRF2." (PMID 40871737, 2025). "Therefore, it is speculated that Trim44 may regulate the ubiquitination level of TLR4 in myocardium, affecting the activation state of the AKT/mTOR signaling pathway and thus participating in the regulation of cardiac hypertrophy." (PMID 35855640, 2023).
cardiac hypertrophy (continued). "Cardiac hypertrophy is required to maintain contractile function and pump sufficient blood throughout the peripheral organs in the face of increased afterload, but persistent hyperactivation of hypertrophic signaling results in cardiac dysfunction, such as aberrant activation of mTOR and YAP6,13,31." (PMID 37726310, 2023). "When the PI3K/Akt/mTOR pathway was inhibited, a more prominent decrease in cardiac hypertrophy, NF-κB, and IκBb was noted, providing evidence that TLR4 downstream metabolites can be affected by different TLR pathways which could be contributing to cardiac hypertrophy." (PMID 38140398, 2023). "Therefore, modulation of PTEN/mTOR signaling may have therapeutic effects against cardiac hypertrophy and dysfunction." (PMID 35218467, 2023). "Therefore, many studies have confirmed that activating AKT/mTOR signaling pathways could potentially reduce cardiac hypertrophy." (PMID 36742144, 2023). "Thus, interventions of NRF2 activity via the mTOR pathway may be developed for treating cardiac hypertrophy." (PMID 35185583, 2022). "Therefore, this study provides evidence that mTOR/S6K1/4EBP1/eIF4E signaling pathway may be necessary for the mechanism of the Testosterone-induced OVX SHR myocardial hypertrophy response." (PMID 34874016, 2022). "However, the function of miR-337-5p and its potential contribution to the serine/threonine-protein kinase, a mammalian target of rapamycin (mTOR) signaling in cardiac hypertrophy remains unknown." (PMID 34515612, 2021). "However, whether the AKT/mTOR signalling pathway was involved in the treatment effect of EGCG for cardiac hypertrophy and fibrosis remains unclear." (PMID 34607503, 2021). "However, it has been unclear whether Y-Sesn2 KO mice enhances cardiac hypertrophy through activation of mTOR." (PMID 32863202, 2020). "Notably, in rat model of cardiac hypertrophy berberine could attenuate left ventricular remodeling and cardiomyocyte apoptosis through an autophagy-dependent mechanism via inhibition of mTOR, p38 and ERK1/2 MAPK signaling pathways." (PMID 33101051, 2020). "In addition, CTS activate phosphatidylinositol 3-kinase, thus leading to stimulation of the Akt (aka protein kinase B) and mechanistic (aka mammalian) target of rapamycin (mTOR) pathway, which is thought to be particularly important in relation to cardiac hypertrophy." (PMID 33101052, 2020). "Thus, in the process of regulating ventricular hypertrophy mTOR is involved." (PMID 32372974, 2020). "We found that BZP could inhibit angiotensin II (Ang II)‐induced cardiomyocyte hypertrophy and excessive autophagy through AMP‐activated protein kinase (AMPK)‐mammalian target of rapamycin (mTOR) signalling and could ameliorate pressure overload‐induced cardiac hypertrophy and heart dysfunction." (PMID 31222939, 2019). "In addition, mTOR signaling during DM may result in cardiac hypertrophy, promote some of the ill effects of hyperleptinemia, and further diabetic retinopathy given the ability of mTOR to promote angiogenesis." (PMID 22545721, 2012). "As expected, each of the phosphorylation levels of mTOR, ERK, TnI, PKD, HDAC5 and PLN was increased in PE-stimulated cardiomyocytes, supporting the use of PE stimulation as a suitable in vitro model of cardiac hypertrophy." (PMID 41596248, 2026). "A rat model of cardiac hypertrophy induced by prolonged swimming was used to investigate the relationship between microRNAs and the PI3K/AKT/mTOR pathway." (PMID 40463932, 2025). "Our findings suggest that MARCH5 participates in the pathological cardiac hypertrophy by regulating the Akt/mTOR/Gsk‐3β/GATA4 pathway, positioning it as a promising therapeutic target for cardiac hypertrophy." (PMID 40753540, 2025). "In vivo, we further confirmed that PGAM2 knockdown alleviated cardiac hypertrophy through downregulation of HSP90 and mTOR/IKKα signaling pathway." (PMID 39897023, 2025).
cardiac hypertrophy (continued). "In this study, MYL3 was found to regulate the PI3K/Akt/mTOR and ERK signaling pathways, thereby promoting autophagy and aggravating myocardial hypertrophy." (PMID 40007621, 2025). "In the present study, Ang II was found to induce myocardial hypertrophy, fibrosis, oxidative stress, and inflammation, as evidenced by alterations in the PI3K/AKT1/mTOR/ERK, TGF-β/Smad2/3, NF-κB, and NOX1 signaling pathways." (PMID 39715792, 2025). "Further, DIM stimulated p-AMPK-α and disrupted the mammalian target of rapamycin (mTOR) and MAPK signaling response to Ang II, confirms the amelioration of cardiac hypertrophy." (PMID 40094833, 2025). "For example, allicin attenuated myocardial hypertrophy by activating PI3K/AKT/mTOR and ERK/mTOR signaling." (PMID 41007776, 2025). "Agonists like liraglutide protect against cardiac hypertrophy and fibrosis by activating the AMPK/mTOR/p70S6K pathway and ATP‐sensitive potassium channels." (PMID 40070049, 2025). "In our present study, we demonstrate that PGAM2 is involved in the regulation of mTOR and IKKα/ NFκB signaling through modulation of HSP90 stability, ultimately contributing to Ang II-induced cardiac hypertrophy." (PMID 39897023, 2025). "In summary, our study demonstrated for the first time that PGAM2 played important role in regulating pathological cardiac hypertrophy through interacting and modulating HSP90 stability and its downstream mTOR and IKKα / NFκB signaling." (PMID 39897023, 2025). "Some research has confirmed that the AMPK/mTOR signaling pathway can be involved in the advancement of CVDs, containing myocardial ischemia/reperfusion injury(MIRI), AS, myocardial hypertrophy, etc., Studies the regulation of autophagy." (PMID 40491718, 2025). "Mechanistic studies indicated that MARCH5 directly interacted with Akt, enhancing the phosphorylation of Akt, mTOR and Gsk3β, thereby increasing GATA4 expression and aggravating cardiac hypertrophy." (PMID 40753540, 2025). "Studies have shown that MYL3 can interact with circRNA (circ-0001283) to regulate protein stability and activate PI3K/Akt/mTOR- and ERK-mediated autophagy signaling, thereby promoting cardiac hypertrophy progression." (PMID 40725470, 2025). "Panax ginseng stem and leaf saponins ameliorate cardiac hypertrophy by down-regulating LC3B, Beclin-1 and p62 expressions through the PI3K/Akt/mTOR axis, and suppressing aberrant autophagy and apoptosis, thus exerting a cardioprotective effect in rats." (PMID 40491718, 2025). "Metformin can promote autophagy throughthe mTOR signaling pathway, inhibit the activation of NLRP3 inflammasome,regulate cell pyroptosis, and alleviate cardiac hypertrophy." (PMID 39484135, 2024). "In angiotensin II-induced cardiac hypertrophy H9C2 cell models, the sEH inhibitor TUPS inhibits autophagy by activating the mTOR signaling pathway, reducing the expression of cardiac hypertrophy markers ANP and BNP, and alleviating cardiac hypertrophy." (PMID 38628644, 2024). "miR-140 impacts cardiac hypertrophy, modulating hypertrophic signaling by targeting genes like PI3K/Akt and mTOR." (PMID 39595980, 2024). "In our study, we observed that the prohypertrophic signal ET-1 induced the inhibition of Akt/mTOR signaling during cardiac hypertrophy, and DGKζ significantly attenuated cardiac hypertrophy by regulating the AKT/mTOR pathway." (PMID 38250603, 2024). "Our results indicate that during the anti-cardiac hypertrophy effects of GQ262, the protein levels of p-Akt and p-mTOR are significantly reduced." (PMID 39408627, 2024). "miR-200a induces cardiac hypertrophy through the downregulation of TSC1, thus relieving its inhibition of mammalian target of rapamycin (mTOR) signaling." (PMID 37175451, 2023). "In summary, our results demonstrate that G1 can attenuate cardiac hypertrophy and fibrosis and improve the cardiac function of mice in the OVX + TAC group through AKT/mTOR mediated inhibition of autophagy." (PMID 36674423, 2023).
cardiac hypertrophy (continued). "Several signaling pathways, including PTEN/AKT/mTOR, MAPK, and calcineurin/NFAT signaling pathways regulate cardiac hypertrophy." (PMID 35218467, 2023). "In contrast, activating the mTOR pathway reduces Eef2 phosphorylation by inhibiting EF2K, and previous research has shown Eef2 to be upregulated during cardiac hypertrophy." (PMID 37378715, 2023). "Fibrate has been reported to inhibit cardiac hypertrophy and heart failure through suppression of PI3K/Akt/mTOR signaling and regulation of HMGB1 expression, in addition to activation of PPARα." (PMID 35055179, 2022). "Resveratrol can upregulate autophagy, downregulate oxidative stress and apoptosis through PI3K/AKT/mTOR pathway, significantly improve the ejection fraction of chronic intermittent hypoxia (CIH) rats, and inhibit myocardial hypertrophy and cardiac remodeling." (PMID 36120366, 2022). "Mechanically, we constructed in vivo and in vitro cardiac hypertrophy models to investigate the crosstalk between MAPK and MTOR." (PMID 35433687, 2022). "It is known that mTOR plays a crucial role in maintaining oxidative equilibrium, is involved in the degradation of NRF2, and acts upstream of NRF2 in Ang II-induced cardiac hypertrophy." (PMID 36430296, 2022). "XN also reduces cardiac hypertrophy and fibrosis induced by isoprenaline via the PTEN/AKT/mTOR mechanism." (PMID 36615756, 2022). "On the other hand, rapamycin abolished the effects of testosterone-induced cardiac hypertrophy, decreased the systolic and diastolic blood pressure of SHR, and inhibited the activation of mTOR/S6K1/4EBP1 signaling pathway in a concentration-dependent manner." (PMID 34874016, 2022). "A major finding in our study is that testosterone-mediated changes in the expression level of myocardial mTOR/S6K1/4EBP1/eIF4E signaling pathway play a critical role in the pathogenesis and development of cardiac hypertrophy in SHR after ovariectomy." (PMID 34874016, 2022). "As a result, Ly6Clow macrophages activated the amphiregulin-induced AKT/mTOR signaling pathway, and Ly6ClowMHCIIhigh macrophage polarization increased expression levels of osteopontin and TGF-β, which led to myocardial hypertrophy and fibrosis." (PMID 34135897, 2021). "In a separate study using a transverse aortic constriction-induced cardiac hypertrophy mouse model, the authors found that PKD1 contributed to cardiac hypertrophy through inhibiting AKT/mTOR regulated cardiac autophagy." (PMID 33807058, 2021). "It was observed that PI3K, AKT, GSK3β, mTOR, P70S6K, and eIF-4E were significantly phosphorylated in TAC mice, suggesting that PI3K-Akt signaling pathway was indeed activated in cardiac hypertrophy." (PMID 33778070, 2021). "As a dual mTOR kinase inhibitor, AZD2014 demonstrates preventive effects against PE-induced cardiac hypertrophy in vitro and Mybpc3-related HCM phenotypes in vivo." (PMID 34674743, 2021). "It has also been reported to attenuate cardiac hypertrophy via regulation of ROS-dependent signalling pathways, and Nrf2 antioxidant signalling pathways, and activating PI3K/Akt/mTOR and MAPK/ERK/mTOR pathways." (PMID 35052591, 2021). "As expected, it was observed that PI3K, AKT, GSK3β, mTOR, P70S6K, and eIF-4E were significantly phosphorylated in the TAC group, suggesting that PI3K-Akt signaling pathway was indeed activated in cardiac hypertrophy." (PMID 33778070, 2021). "mTOR is the pivotal upstream activator of S6K1 and 4EBP1 and contributed significantly to cardiac hypertrophy." (PMID 34059001, 2021). "Mechanistic in vivo and in vitro studies demonstrated that miR-17-5p suppresses autophagy to promote cardiac hypertrophy by inhibiting Mfn2 expression, and activating the phosphatidylinositol-3-kinase (PI3K)/AKT/mammalian target of rapamycin (mTOR) pathway." (PMID 34869689, 2021).